EGFR (epidermal growth factor receptor)
Diseases named in the same sentence as EGFR in open-access papers (continued):
Sharing a sentence is not in itself a finding about the gene and the disease.
tumor (continued). "Furthermore, the cetuximab-induced inhibition of EGFR repressed tumor burden in xenograft HNSCC models." (PMID 25723392, 2015). "Percentage tumor evaluation and macrodissection underpin most of the new and emerging molecular tests for solid tumors including RAS, EGFR, BRAF mutational analysis, commercial tests such as Oncotype DX, Mammaprint, Prolaris and more recent clinical sequencing panels (e.g. Foundation One)." (PMID 26317646, 2015). "EGFR is involved in the tumor angiogenesis of HNSCC via the HIF-1α and Notch1 pathways." (PMID 25723392, 2015). "Their method is based on micro-dissection of tumor cells directly into PCR buffer, followed by amplification, and determination of EGFR status by fragment length analysis of fluorescently-labeled products (exon 19 deletions) or TaqMan Assay (exon 20 T790M and exon 21 L858R)." (PMID 26022577, 2015). "Moreover, EGFR mRNA expression was inversely related to age (p = 0.003), post-menopausal status (p = 0.003) and tumor size (p = 0.001)." (PMID 26021752, 2015). "This may result in insufficient circulating anti-EGFR mAbs to reach tumor lesions, prohibiting antitumor activity." (PMID 26309164, 2015). "After treatment, patients with ESCC expressing high levels (2+ and 3+ expression) of EGFR had a median OS of 13 months compared to 10 months in patients with an ESCC tumor showing a low level of EGFR expression, although this difference was not statistically significant (p = 0.537)." (PMID 26392415, 2015). "Interestingly, well-differentiated keratinizing tumor cells expressed high levels of EGFR by immunohistochemistry, yet had significantly lower local fluorescence." (PMID 26120042, 2015). "T790M mutations exists as dominant clones in about 50% of patients with acquired resistance, and subclonal populations of EGFR mutant tumor cells with or without the T790M mutation can coexist in EGFR mutant NSCLC that has acquired resistance to EGFR-TKIs." (PMID 26334838, 2015). "In addition, saracatinib offers the advantage of simultaneous EGFR/Src inhibition, possibly providing a further benefit in terms of tumor growth control and preventing the onset of Src-mediated resistance to EGFR inhibitors, as previously reported." (PMID 26325669, 2015). "However, we did find that tumor LNM, stage, proliferation rate measured by Ki-67 staining, and EGFR overexpression were significantly associated with patient DFS in a univariate analysis." (PMID 26115045, 2015). "It is hypothesized that pUS-MB exposure can enhance blood-tumor permeability and prolong the circulation of the targeting MBs and enhance the local concentration of therapeutic EGFR delivery at the local tumor site to provide therapeutic efficacy." (PMID 25960704, 2015). "The relationship between PD-L1 expression and age, gender, histopathological type, tumor stage and EGFR mutational status was not significant, except for the line of EGFR TKIs (P = 0.041)." (PMID 25895031, 2015). "Therefore, it is important to understand inter-tumour heterogeneity of acquired resistance mechanism(s) in a single patient after treatment failure of EGFR-TKIs." (PMID 26400668, 2015). "The identification of model systems to investigate or validate strategies to disrupt EGFR-dependent tumor cell growth is critical and may provide the basis for clinical applications." (PMID 26580964, 2015). "On the other hand, EGFR expression has been linked to GSC phenotype, and may contribute to the aggressive behavior of tumor-initiating cells." (PMID 26230711, 2015). "EGFR-tyrosine kinase inhibitors (EGFR-TKIs) can competitively inhibit the ATPs binding to the intracellular areas of EGFR and block its signaling pathway, thus achieving the anti-tumor effect." (PMID 26474174, 2015). "Thus, persistently up-regulated EGFR signaling for tissue repair appeared to be hijacked for neoplasia program in the lungs of Gprc5a−/− mice following silica exposure." (PMID 26447616, 2015).
tumor (continued). "Cancer-associated fibroblasts (CAFs), essential components of the tumor microenvironment, may also modulate EGFR treatment sensitivity and promote tumor growth." (PMID 26437222, 2015). "However, despite the initial disease control, tumor relapse is inevitably observed after a median of 9-14 months, indicating the development of acquired resistance to EGFR-TKIs in these patients." (PMID 25823662, 2015). "LeY is one of the glycoproteins carried by EGFR, changes of EGFR glycosylation may activate growth-factor receptor tyrosine kinases and promote tumor proliferation." (PMID 25672851, 2015). "Cetuximab directly inhibits tumour growth, induction of apoptosis, inhibition of angiogenesis, inhibition of metastasis, and also exerts anti-angiogenic effects by blocking ligand-induced phosphorylation of EGFR on endothelial cells." (PMID 26517691, 2015). "However, in that study, tumors were regarded as EGFR positive if tumor cell membranes stained positively with anti-EGFR antibody in IHC in more than 10 % of tumor cells." (PMID 26673416, 2015). "Since both these pathways are involved in inflammation and EGFR signaling that will lead to tumor cell growth, use of agents that combined inhibit both pathways simultaneously may provide synergy for improved tumor inhibition." (PMID 26429877, 2015). "Further increases in tumor concentration (>10 μM) were associated with decreased phosphorylation of HER3 and increased EGFR, consistent with a switch in HER3 heterodimers from HER3/HER2 to HER3/EGFR, or formation of EGFR homodimers." (PMID 26571496, 2015). "Therefore, we believe that h-R3-dendriplex is a promising targeted gene delivery candidate, especially in EGFR-overexpressing tumor cells." (PMID 26309162, 2015). "Interestingly, EGFR-independent phosphorylation of STAT3 has been identified as a mechanism of tumor resistance to agents targeting SFK." (PMID 25779657, 2015). "The frequency of EGFR gene mutations was similar in cytological and histological specimens, and in primary and metastatic lesions, and did not depend on the percentage of tumor cells and quality of isolated DNA." (PMID 25086987, 2015). "Therefore inhibition of EGFR and its downstream signalling pathways presents a promising strategy to prevent tumor progression." (PMID 25918252, 2015). "Similarly, PDT + C225, an EGFR inhibitor, produced synergistic reductions in mean tumor burden when compared with PDT only or C225." (PMID 25918252, 2015). "As it has been widely accepted that most solid tumors, including lung tumors, arise and are maintained by CSCs, and that chemotherapy-spared CSCs are responsible for tumor recurrence, it is clear that biomarkers predicting erlotinib response in EGFR-WT tumors have to be determined at the CSC level." (PMID 26247735, 2015). "However, many patients also harbour multiple EGFR-TKI-refractory tumours simultaneously at the time of tumour burden." (PMID 26400668, 2015). "The TKI gefitinib inhibits growth in some tumor types by targeting EGFR." (PMID 25762314, 2015). "It remains to be defined whether this is a global downregulation of EGFR in all tumor cells or is a positive selection of cells with lower EGFR expression." (PMID 25887735, 2015). "Also, GnT-III is reported to add bisecting GlcNAc to epidermal growth factor receptor (EGFR) on plasma membrane of tumor cells." (PMID 26222427, 2015). "Moreover, the aberrant expression of EGFR has an important role in the development and growth of tumor cells." (PMID 25699271, 2015). "This detailed mechanism confirmed that EGFR mutant NSCLC patients may benefit not only from direct tumor killing effect of EGFR-TKIs but also indirectly from immune enhancement after EGFR-TKIs treatment." (PMID 25895031, 2015). "Moreover, alterations in growth factor receptors other than EGFR were seen in four of five AIS tumours." (PMID 26374070, 2015).
tumor (continued). "When propagated in the absence of serum, tumor spheroids retained EGFR amplification and an associated polysomy of chromosome 7 as determined by FISH analysis." (PMID 26136784, 2015). "We hypothesized that adding erlotinib to chemotherapy could improve early tumor response in EGFR-positive BTC tumors." (PMID 26189560, 2015). "Our results demonstrate that TG101348 could overcome erlotinib-resistance and enhance the anti-tumor action of erlotinib in EGFR-mutant NSCLC cells." (PMID 25869210, 2015). "In patients who do not respond to this therapy, it has been demonstrated that the tumour cells carried one of the mutations of the KRAS gene, which is found located on the EGFR gene pathway, which caused the activation of this pathway independently of the EGFR blocking." (PMID 25932044, 2015). "The uncovering of the epidermal growth factor receptor (EGFR) responsible for cell proliferation and survival as being constitutively over-expressed in the majority of these tumour types, prompted the development of a number of anti-EGFR agents for NSCLC treatment." (PMID 25918681, 2015). "Importantly, because there are a certain number of mCRC patients with molecular alteration other than KRAS exon 2, further refinement of tumor-specific genetic markers is needed to improve the efficacy of anti-EGFR therapy." (PMID 25886136, 2015). "Conversely, the implication from our results is that EGFR-TKI may suppress tumor sensitivity to NK cells via down-regulation of the expression of NKG2D ligands, as was shown by the attenuation of NK cell-mediated cytotoxicity by Gefitinib." (PMID 26439264, 2015). "We have included in our study data pertaining to the EGFR mutational status of 32 characterised patients (tumour tissue was not available for the remaining subjects)." (PMID 25918681, 2015). "The pathologic results were reviewed regarding the size, histological type, histological grade, estrogen receptor (ER) and progesterone receptor (PR) status, human epidermal growth factor receptor 2 (HER2), epidermal growth factor receptor (EGFR), and Ki-67 of the primary tumor." (PMID 25889560, 2015). "Following the downregulation of Cbl in peritumoral liver tissue, the EGFR level increased sharply owning to decreased ubiquitylation and degradation of EGFR, which in turn promotes angiogenesis and inflammatory cells infiltration, thus favoring dormant neoplasm progression ultimately." (PMID 26474280, 2015). "Moreover, the profound anti-tumor activity of 244-MPT across xenografts expressing T790M EGFR in vivo suggests a great potential to target T790M-expressing tumors." (PMID 26517520, 2015). "One could postulate that insufficient cetuximab was available for uptake in tumor lesions due to sequestration in the liver or other EGFR expressing organs." (PMID 26309164, 2015). "The SUVmax was significantly different according to the tumor grade, ER, EGFR, and Ki-67 for IDCs." (PMID 25889560, 2015). "Cisplatin is one of these stimuli, which may lead to nuclear EGFR translocation in tumor cells and resistance to treatment, as result of an enhanced DNA repair." (PMID 25784483, 2015). "Our data suggest that EGFR-driven overexpression of IFRD1 may also play a role in deregulating NFκB-signalling in HPV-induced tumour cells." (PMID 26055519, 2015). "Cetuximab and Panitumumab are mAbs that bind to EGFR, possessing anti-tumor activity." (PMID 26635612, 2015). "Indeed HSP90 inhibitors have been shown to downregulate the expression of mutant epidermal growth factor receptor in tumors and selectively kill tumor cells." (PMID 26334999, 2015).
tumor (continued). "In contrast, if the tumor is EGFR high/p-Akt high, the RTK signals besides EGFR may play important roles in activating Akt." (PMID 26124180, 2015). "When we stained for CD71 instead of EGFR to identify KLM-1 tumor cells, we found that KLM-1 cells stained with anti-CD71 R-Phycoerythrin (R-PE) were 40-fold brighter than background and have a peak clearly distinguishable from unstained cells, unlike the cells stained for EGFR." (PMID 26111884, 2015). "Since in tumor cell lines, c-Met phosphorylation can result from EGFR activation, parallel inhibition of EGFR and c-Met could increase the clinical benefit due to synergistic effects of tivatinib and erlotinib or gefitinib." (PMID 26729094, 2015). "Because activation of IGF-1R-mediated signaling has been associated with cancer cell resistance to anti-EGFR therapy and also to RT 16,17, cotargeting EGFR and IGF-1R pathways in conjunctions with RT is expected to yield a better outcome in controlling tumor growth." (PMID 25355701, 2015). "The mechanisms underlying these effects clearly need further attention, but our data indicate a strong inhibitory effect of PROG alone and in combination with TMZ on the EGFR/PI3K/Akt/mTOR signaling which promotes tumor cell proliferation and inhibits apoptosis." (PMID 26110872, 2015). "Noninvasive approaches of evaluating EGFR gene mutation status using substitutes for tumor tissues would be of value for patients in whom sufficient tumor tissue is not available." (PMID 26047516, 2015). "Moreover, the radiation dependent activation of EGFR was found to be Src dependent in some tumor cell lines." (PMID 26546517, 2015). "However, anti-EGFR monoclonal antibodies were detected within the tumor vessels in the targeting MB group, and in both tumor vessels and tissue in the targeting MB combined with pUS group." (PMID 25960704, 2015). "Indeed, cofilin-1 signaling plays a pivotal role in the regulation of efficient EGFR vesicular trafficking in invasive tumor cell." (PMID 25784483, 2015). "Finally, it is important to mention a recent study published by Wilhelm and colleagues confirming the biological role of DCD as biomarker for cellular resistance of various tumor cells to the EGFR/ErbB1 tyrosine kinase inhibitors erlotinib and lapatinib." (PMID 25879571, 2015). "Thus, intermittent high-dose treatment of EGFR-mutant tumors with erlotinib enhanced tumor control with limited toxicity." (PMID 26540572, 2015). "Investigating the same six xenografts’ response to each of three therapies: cisplatin, cetuximab, and radiation, provided a controlled environment in which to relate tumor responses to the pre- and posttreatment expression of five potential predictive biomarkers: EGFR, pEGFR, pAkt, pERK, and ERCC1." (PMID 25619980, 2015). "Together, these findings suggest that the activation of EGFR signaling is correlated with stroma remodeling in tumor recurrence, and that inhibition of EGFR signaling may help delay recurrence." (PMID 26581390, 2015). "In line with a recent report 20 minutes of treatment with 10μM of erlotinib potently suppressed tumor cell growth of the erlotinib sensitive cell lines HCC827 and PC9 (both carry EGFR exon 19 deletion mutations) as effectively as a continuous 72 hours exposure with 0.1μM." (PMID 26540572, 2015). "We first found that Linc00152 could promote tumor growth through EGFR-mediated PI3K/AKT pathway which may serve as potential targets for therapy in the future." (PMID 26538117, 2015). "The authors found that it was the pre-treatment, rather than co-treatment or post-treatment, of a subset of TNBCs with Epidermal Growth Factor Receptor (EGFR) inhibitors that can enhance the sensitivity of tumour cells in their apoptosis response to DNA-damaging chemotherapy." (PMID 25707537, 2015).
tumor (continued). "Experimental systems to retain EGFR amplification present in the original tumor have thus largely relied on immediate orthotopic implantation of freshly resected tissue from GBM with EGFR amplification into nude mice and by subsequent serial passaging in vivo of these xenograft tumors." (PMID 26136784, 2015). "EGFR levels were increased in the transplanted tumor treated with rAd-ASPP2." (PMID 25980493, 2015). "In addition, testing of cfDNA demonstrated acceptable concordance (BRAF, 91%; EGFR, 99%; KRAS, 83%; PIK3CA, 91%) with standard of care mutation analysis of primary or metastatic tumor tissue obtained during clinical care." (PMID 25980577, 2015). "Inhibition of EGFR could effectively increase anti-tumor activity of agents targeting other signaling pathways, such as STAT3 or AKT." (PMID 25928246, 2015). "In summary, we have determined that cetuximab-IONPs bind to both the wtEGFR and the EGFRvIII deletion mutant on human patient-derived GBM cells (including GSCs), inhibit EGFR cell signaling, are internalized by the tumor cells, and promote internalization of the EGFR resulting in enhanced apoptosis." (PMID 25871395, 2015). "Furthermore, in the current study we enriched for EGFR/EGFRvIII and used EGFR protein levels to identify tumour exosomes." (PMID 25959588, 2015). "Interestingly, the cytosolic EGFR expression in the lymph node is higher than the expression in the paired sections of primary tumor." (PMID 26497368, 2015). "In conclusion, erlotinib offers a potentially cost-effective treatment option for the subgroup of predominantly poor performance patients with NSCLC with EGFR wild-type tumours who develop first-cycle rash and who are considered unfit by clinicians to be treated with first-line chemotherapy." (PMID 26137881, 2015). "Despite the apparent important role of EGFR in CC development, EGFR inhibitor therapy revealed also only modest benefit in CC patients and it remains to be investigated whether, similar to HCCs, the EGFR plays a tumorigenic function in non-tumor cells." (PMID 26729094, 2015). "In addition, it will be important to extend the tumor profiling studies to include CIP4 expression relative to EGFR levels, and downstream targets that were affected by CIP4 silencing." (PMID 25823823, 2015). "Because of the low number of patients with EGFR mutations, we did not perform analysis to test associations between the amount of mutant cfDNA and the rate of discrepancies (tumor tissue vs. cfDNA)." (PMID 25980577, 2015). "Both synergized with EGF/EGFR to accelerate tumor cell motility and invasion." (PMID 26635609, 2015). "As shown in the relationship between small EGFR-TKI and EGFR mutation, the ability of TAE226 to compete with ATP, resulting in its anti-tumor potential, is determined by two factors: 1) the binding ability for TAE226 to mutant EGFR and 2) the affinity for ATP to mutant EGFR." (PMID 26090892, 2015). "The simultaneous targeting of both signaling pathways with an EGFR x c-MET bispecific antibody (BsAb) could produce synergies that more effectively block tumor proliferation and metastasis (21, –, 23)." (PMID 26260789, 2015). "Given the high efficacy of high-dose treatment of erlotinib in EGFR-mutant tumor cells in vitro, we tested whether pulsatile high doses of erlotinib enhanced tumor control in vivo." (PMID 26540572, 2015). "While multiple AAHs or MIA tumours may share common alterations (such as BRAF or EGFR, respectively), specific mutations are limited to individual patients in relatively more heterogeneous AIS tumours." (PMID 26374070, 2015). "It was further reported that the inhibition of EGFR in a time-staggered way may be responsible for sensitising tumour cells to genotoxic drugs." (PMID 25707537, 2015). "In the present study, 56% of patients harbored activating EGFR mutations, while tumor EGFR expression was observed in 85% of all patients, regardless of their EGFR genotype." (PMID 26439803, 2015).